POLR3G (RNA polymerase III subunit G)
Diseases named in the same sentence as POLR3G in open-access papers (continued):
Sharing a sentence is not in itself a finding about the gene and the disease.
acute myeloid leukemia (3 papers, 2022 to 2023). Acute myeloid leukemia (AML) is a group of neoplasms arising from precursor cells committed to the myeloid cell-line differentiation. "Analogous gene expression profiling in immune cells isolated from patients with acute myeloid leukemia (AML) identifies co-expression of both POLR3G and POLR3GL mRNA in pre-leukemic hematopoietic stem cells (pHSCs), leukemia stem cells (LSC), and leukemic blast cells (Blast)." (PMID 35637192, 2022). "This phenomenon is flipped for POLR3G and POLR3GL in acute myeloid leukemia (LAML), however, suggesting a potentially unique role of RPC7α and RPC7β in myeloid cells with implications for disease progression." (PMID 37894362, 2023). "Beyond the embryonic transcription factors OCT4, NANOG, and putative miR-1305 interference, POLR3G expression is also regulated by MYC and sensitive to MYC disruption in cancers featuring MYC upregulation, including colon carcinoma and acute myeloid leukemia cell lines." (PMID 36710885, 2022).
cholangiocarcinoma (2 papers, 2020 to 2022). A carcinoma that arises from the intrahepatic biliary tree (intrahepatic cholangiocarcinoma) or from the junction, or adjacent to the junction, of the right and left hepatic ducts (hilar cholangiocarcinoma). "TIMER analyses revealed that POLR3G expression was up-regulated in multiple cancer types, including cholangiocarcinoma, colon adenocarcinoma, esophageal carcinoma, kidney renal clear cell carcinoma." (PMID 33194434, 2020).
lung adenocarcinoma (2 papers, 2022). A carcinoma that arises from the lung and is characterized by the presence of malignant glandular epithelial cells. "Our study also revealed that high expression of NME4 and POLR3G may adversely affect the poor prognosis of lung adenocarcinoma." (PMID 34996932, 2022).
lung cancer (2 papers, 2025). A malignant neoplasm involving the lung. "POLR3G can regulate the stemness of lung cancer and the metastasis of triple‐negative breast cancer." (PMID 39964093, 2025).
multiple myeloma (2 papers, 2022 to 2023). "Notably, high POLR3G expression is associated with poor survival outcomes in a variety of cancers, including transitional cell carcinoma, multiple myeloma, hepatocellular carcinoma, and lung adenocarcinoma." (PMID 37894362, 2023). "Notably, POLR3G upregulation has been linked with poor survival outcomes across a variety of cancers, including in patients with lung adenocarcinoma, hepatocellular carcinoma, transitional cell carcinoma, multiple myeloma, and other forms of cancer." (PMID 36710885, 2022). "The mutually exclusive incorporation of either RPC7α (POLR3G) or RPC7β (POLR3GL) distinguishes two forms of RNA polymerase III, Pol IIIα and Pol IIIβ, first identified in mouse myeloma tumor cells and subsequently discovered in human cells." (PMID 37894362, 2023). "In addition to the spatiotemporal regulation and dynamic replacement of subunit RPC7α with RPC7β during early development, POLR3G expression re-emerges in proliferative and transformed cells, in line with the discovery of both Pol IIIA and IIIB in mouse myeloma tumor cells." (PMID 36710885, 2022).
prostate tumor (2 papers, 2020 to 2022). "Another study found that the expression of POLR3G was up to three-fold higher in prostate tumors compared to normal adjacent samples." (PMID 33194434, 2020).
triple-negative breast carcinoma (2 papers, 2022 to 2023). An invasive breast carcinoma which is negative for expression of estrogen receptor (ER), progesterone receptor (PR), and human epidermal growth factor receptor 2 (HER2). "RT-qPCR analyses showed that POLR3G mRNA was more than three-fold overexpressed in all triple-negative breast cancer cell lines (TNBC-CL) whereas POLR3GL expression levels were below those of the non-tumorigenic control." (PMID 36497214, 2022). "Thus, we conclude that POLR3G expression regulates tumorigenesis and the expression of genes that are involved in cell fate decisions in triple-negative breast cancer." (PMID 36497214, 2022). "MYC also raises the expression of POLR3G, a pol III subunit that promotes tumour growth and metastasis in triple-negative breast cancer." (PMID 37509247, 2023).
breast invasive carcinoma (1 paper, 2022). "This relationship is not observed in contexts where POLR3G upregulation is less common (breast invasive carcinoma and thyroid carcinoma), together suggesting Pol III transcription dysregulation may be a pronounced feature in a multitude but subset of cancer contexts." (PMID 35637192, 2022).
breast tumors (1 paper, 2022). "The top eight genes that negatively correlated to POLR3G expression (MLPH, FOXA1, SPDEF, AR, SIDT1, AGRP2, XBP1, GATA3) are typically overexpressed in ER+ breast tumors as compared to ER- breast tumors." (PMID 36497214, 2022).
clear cell renal cell carcinoma (1 paper, 2023). "Consistent with previous findings, POLR3G expression is commonly associated with unfavorable outcomes, most notably in clear cell renal cell carcinoma (KIRC) and brain lower-grade glioma (LGG)." (PMID 37894362, 2023).
leukemia (1 paper, 2022). A malignant (clonal) hematologic disorder, involving hematopoietic stem cells and characterized by the presence of primitive or atypical myeloid or lymphoid cells in the bone marrow and the blood. "Direct visualization of individual genes highlights this relationship: gene accessibility is low in differentiated immune cell lineages and high in progenitor and leukemia-related contexts with high POLR3G gene expression." (PMID 35637192, 2022).
tumor (14 papers, 2016 to 2025). "RNA polymerase III (Pol III) subunit RPC7α, which is encoded by POLR3G in humans, has been linked to both tumor growth and metastasis." (PMID 37894362, 2023). "Overall, POLR3G expression was associated with race, tumor status, tumor subtype, T classification, and pathological stage." (PMID 33194434, 2020). "Gene set enrichment analysis (GSEA) was performed to explore the associated gene sets enriched in different POLR3G expression phenotypes and the online tool Tumor IMmune Estimation Resource (TIMER) was used to explore the correlation between POLR3G expression and tumor immune infiltration in TCC." (PMID 33194434, 2020). "Our survey of POLR3G-chromatin correlation scores, on the other hand, connects genome-wide accessibility profiles in 409 tumor samples to integrated mRNA profiles in matched samples." (PMID 37894362, 2023). "Our chromatin correlation survey indicates that DNA accessibility downstream of the POLR3G transcription start site is the most significant predictor of POLR3G expression surveyed across 409 tumor samples." (PMID 37894362, 2023). "The here presented data identify POLR3G/RPC32α as an important regulator of TNBC tumor growth and generation of metastases in vitro and in mouse xenografts." (PMID 36497214, 2022). "Here, we show that POLR3G/RPC32α expression regulates tumor formation and dissemination in vitro and in vivo." (PMID 36497214, 2022). "GSEA analysis showed that several gene sets associated with tumor development and metastasis, including TGF-β signaling, PI3K-AKT-mTOR signaling, and IL6-JAK-STAT3 signaling, were significantly enriched in POLR3G high expression phenotype." (PMID 33194434, 2020). "More specifically, POLR3G expression was negatively correlated with tumor purity, and positively correlated with the infiltrating levels of CD8+ T cells, neutrophil cells, and dendritic cells in TCC." (PMID 33194434, 2020). "We also found that high POLR3G expression was positively correlated with high T classification, advanced clinical stage, and tumor recurrence, which are strongly correlated with poor prognosis in patients with TCC." (PMID 33194434, 2020). "Taken together, these findings suggest that POLR3G contributes to the regulation of immune cell infiltration and immune checkpoint molecule expression, resulting in the suppression of anti-tumor immunity." (PMID 33194434, 2020). "Whereas POLR3A and POLR3GL were expressed at comparable levels, POLR3G expression was on average 3.7-fold higher in tumours relative to adjacent prostate samples from the same individuals." (PMID 30820548, 2019). "In addition, the POLR3G KO impairs tumor growth and metastasis formation of orthotopic xenografts in mice." (PMID 36497214, 2022). "As well-differentiated tumours generally have better prognosis and POLR3G depletion triggers differentiation of hESC, we hoped it might have similar effects in a model of advanced disease." (PMID 30820548, 2019). "Indeed, POLR3G can be induced by viral and cellular oncogenes and increase the growth of xenograft tumours in mice." (PMID 30820548, 2019). "The differential response may reflect levels of POLR3G, which is more abundant in tumours than in normal cells." (PMID 30820548, 2019). "Importantly, the POLR3G KO impairs tumor growth and metastasis of intraductal xenografts in mice." (PMID 36497214, 2022). "The target gene of miR‐7‐1‐3p, POLR3G, is regulated by the transcription factor MYC and is highly expressed in embryonic stem cells and some tumor cells." (PMID 39964093, 2025). "POLR3G embryonic regulators OCT4 and NANOG, for example, are markers of cancer stem cells and play important roles in tumor-initiating cells." (PMID 36710885, 2022). "Specific overexpression of POLR3G but not of the paralogous POLR3GL subunit or any other component of the Pol III transcription system in TNBC is indicative of unique tumor-promoting functions of POLR3G in TNBC." (PMID 36497214, 2022).
tumor (continued). "Finally, we used the ssGSEA method to determine the correlations between ANLN, POLR3G, EHBP1, and ERO1A and 24 types of tumor-infiltrating immune cells." (PMID 35769906, 2022). "Integrated analysis of POLR3G and POLR3GL gene expression with predictive chromatin features in individual tumor samples once again identifies positive correlations between SNAR-A and POLR3G expression, further extending this relationship beyond THP-1 and primary immune cells into cancer contexts." (PMID 35637192, 2022). "We then analyzed CALU, KIF1B, and POLR3G expression in TCGA database and NPC microarray GSE53819, the results showed that CALU and POLR3G are highly expressed in HNSC tumor tissues while KIF1B is not significant, but all of them are highly expressed in NPC tissues in GSE53819." (PMID 39964093, 2025). "This hypothesis was also supported by the fact that functions fulfilled by POLR3G in regulating TNBC tumor development and metastasis could not be compensated by POLR3GL expression." (PMID 36497214, 2022). "Expression levels of POLR3G were strongly correlated with T classification (T1-2 vs. T3-4, P = 0.001), pathological stage (stage I-II vs. stage III-IV, P = 0.005), tumor status (tumor free vs. with tumor, P = 0.001), tumor subtype (papillary vs. non-papillary, P < 0.001), and race (P < 0.001)." (PMID 33194434, 2020).
cancer (12 papers, 2019 to 2025). A tumor composed of atypical neoplastic, often pleomorphic cells that invade other tissues. "Here, we perform a genomic survey of both the transcription and chromatin signatures associated with POLR3G mRNA abundance in cancer with the goal of uncovering gene regulatory mechanisms contributing to POLR3G expression." (PMID 37894362, 2023). "Our results point to a multi-layered regulatory structure that juxtaposes broad-acting factors, such as MYC, with a combination of transcription factors and gene-internal enhancer elements linked with POLR3G upregulation in cancer." (PMID 37894362, 2023). "Altogether, these data implicate several additional factors, highlighting the overall complexity of combinatorial gene regulation and further supporting a multimodal model for POLR3G regulation underlying RPC7α re-emergence in cancer." (PMID 37894362, 2023). "Multiple reports have linked high POLR3G (RPC7α) expression with unfavorable outcomes across distinct cancer subtypes; however, few studies have directly compared clinical signatures associated with POLR3G, POLR3GL, or other Pol III subunits." (PMID 37894362, 2023). "ZNF131, for example, is the strongest DNA-binding transcription factor positively linked with POLR3G mRNA abundance in cancer, whereas MAX-dimerization protein 4 (MXD4) is the strongest negative correlate." (PMID 37894362, 2023). "Here the authors report that loss of subunit POLR3G, which re-emerges in cancer, promotes expression of small NF90-associated RNA (snaR-A), a noncoding RNA implicated in cell proliferation and metastasis." (PMID 35637192, 2022). "Several of these pathways are associated with oncogenesis, progression, and metastasis of cancer, suggesting that POLR3G expression contributes to the development, progression, and prognosis of TCC." (PMID 33194434, 2020). "A small molecule pol III inhibitor can cause POLR3G depletion, induce similar differentiation and suppress proliferation and viability of cancer cells." (PMID 30820548, 2019). "Taken together, our findings support a model in which POLR3G expression is determined with multiple factors and dynamic regulatory programs, expanding our understanding of the circuitry underlying POLR3G upregulation and downstream consequences in cancer." (PMID 37894362, 2023). "Pol III subunit G (POLR3G) silencing inhibits the expression of a small non-coding RNA (snaR-A) that is related to cancer proliferation and metastasis, and POLR3G upregulation is associated with poor survival outcomes in several cancers." (PMID 36656267, 2023). "Understanding the multitude of factors that shape POLR3G expression may inform future strategies of inhibiting Pol III transcription and, particularly, the cancer-associated form of Pol III through inhibition of POLR3G." (PMID 37894362, 2023). "The data suggest that POLR3G may suppress cell differentiation and thereby maintain proliferative capacity and phenotypic plasticity, features associated with aggressive cancers." (PMID 30820548, 2019). "Understanding the breadth and potential intersection of transcription factors that regulate POLR3G expression is therefore important for deconstructing the mechanisms of POLR3G upregulation and downstream consequences in cancer." (PMID 37894362, 2023). "ZNF131 was identified as the strongest positive TF correlate of POLR3G expression taken across all cancer subtypes, and we demonstrate that POLR3G expression is in fact sensitive to ZNF131 disruption and overexpression." (PMID 37894362, 2023). "Beyond MYC, our POLR3G co-expression correlation survey identifies specific transcription and chromatin-related factors with even stronger correlation signatures in cancer." (PMID 37894362, 2023). "Our current study leverages large-scale multi-omic data to better understand the molecular underpinnings of POLR3G expression and, consequently, RPC7α upregulation in cancer." (PMID 37894362, 2023).
cancer (continued). "POLR3G expression is generally restricted to the earliest stages of development but re-emerges in cancer, in contrast to more constitutive expression patterns observed for POLR3GL and genes encoding other Pol III subunits." (PMID 37894362, 2023). "We analyzed mRNA and chromatin accessibility signatures captured with RNA-seq and ATAC-seq, respectively, to predict regulatory factors and elements involved in POLR3G upregulation across TCGA cancer subtypes." (PMID 37894362, 2023). "Taken together, the co-expression and chromatin accessibility surveys identify candidate regulatory factors and genomic coordinates of interest related to POLR3G upregulation in cancer." (PMID 37894362, 2023). "Differences are observed in Pol III transcription in contexts overexpressing POLR3G or POLR3GL, and during differentiation-associated loss of POLR3G or re-emergence of POLR3G in cancer." (PMID 36710885, 2022). "Most published studies addressed oncogenic effects of POLR3G/RPC32α in cultured cells and described correlations between its overexpression and cancer development." (PMID 36497214, 2022). "Increased gene expression of POLR3G was involved in the proliferation and differentiation of cancer cells and characterized by poor prognosis." (PMID 35874741, 2022). "We find that SNAR-A gene activity consistently tracks with POLR3G gene expression levels in primary immune cell populations and cancer tissues and represents the dominant dynamic feature of both THP-1 differentiation and POLR3G disruption experiments." (PMID 35637192, 2022). "In fact, pan-cancer comparison of survival signatures across all cancer subtypes reveals that POLR3G expression is the most significant feature and predictor of poor survival outcomes compared with all other Pol III subunits." (PMID 36710885, 2022). "miR-1305 reportedly restricts cancer progression across multiple subtypes, though the connection between miR-1305 and POLR3G expression in cancer remains poorly studied." (PMID 36710885, 2022). "Like POLR3G, high levels of MYC expression are associated with poor survival outcomes in specific and overlapping cancer contexts, evidence of concurrent MYC and Pol III dysregulation." (PMID 35637192, 2022). "The re-emergence of RPC7α in transformed cell lines is concordant with evidence that POLR3G expression increases in a variety of cancers." (PMID 36710885, 2022). "The connections between MYC, POLR3G, and cell proliferation and cancer raise important questions about the significance of POLR3G-enhanced transcription, generally, and the functional activities of snaR-A ncRNA, specifically." (PMID 35637192, 2022). "The role of POLR3G in cancer has also garnered significant interest." (PMID 39039528, 2024). "We find that MYC has a relatively high median z-score, suggesting MYC levels may be broadly important for POLR3G expression in cancer." (PMID 37894362, 2023). "Retinoic acid receptor alpha (RARA) and retinoid X receptor alpha (RXRA), which negatively correlate with POLR3G expression across cancers, are retinoid-activated nuclear receptors that mediate transcriptional programs by forming homo- and heterodimers in the presence or absence of specific ligands." (PMID 37894362, 2023). "The upregulation of POLR3G expression in cancer may be related to changes in either activating and/or repressive mechanisms." (PMID 37894362, 2023). "The biological significance of POLR3G upregulation and downstream activities is made evident by Kaplan–Meier analyses, which identify adverse outcomes for patients with tumors expressing elevated levels of POLR3G mRNA in a myriad of cancer contexts." (PMID 35637192, 2022). "Though POLR3G expression broadly correlates with MYC levels across all cancer types, whether and to what degree MYC activity overlaps OCT4, NANOG, and potentially other context-specific master transcription factors remain important questions." (PMID 36710885, 2022). "Several studies have described the links between POLR3G and cancer." (PMID 33194434, 2020).